Y_RNA (Y RNA )
Gene: Miscellaneous RNA gene on chromosome 8 (74,376,687 to 74,376,793, forward strand). Ensembl gene ENSG00000207417.
Homologues: Orthologues: macaque Y_RNA (95% identical). Paralogues in human: RNY3 (88% identical), Y_RNA (88% identical), RNY3P1 (87% identical), Y_RNA (87% identical), RNY3P14 (86% identical), Y_RNA (86% identical), Y_RNA (85% identical), RNY3P7 (84% identical), Y_RNA (84% identical), RNY3P5 (83% identical), Y_RNA (83% identical), RNY3P11 (82% identical), and 93 more.